APOB (apolipoprotein B)
Diseases named in the same sentence as APOB in open-access papers (continued):
Sharing a sentence is not in itself a finding about the gene and the disease.
dementia (continued). "Additionally, imbalances in the proportions of apolipoproteins, primarily ApoA and ApoB, have been demonstrated in dementia." (PMID 40137160, 2025). "We found lipid-related factors including apolipoprotein A, apolipoprotein B, LDL-C, and HDL-C, which are highly correlated with cardiometabolic disorders, were significant mediators of the association between sex and incident dementia." (PMID 36617573, 2023). "The associations between a wider panel of lipids, such as apolipoprotein A (ApoA) and apolipoprotein B (ApoB), as well as lipoprotein A (Lp(a)), with the risk of dementia have not been extensively examined." (PMID 36247924, 2022). "Rather surprisingly, analysis in men restricted to non‐APOE ε4 or non‐APOE ε2 carriers suggested a protective association of elevated TC, LDL‐C, non‐HDL‐C (and ApoB for non‐APOE ε2 carriers) with dementia but this was not the case for mortality or CHD, where results were in the expected direction." (PMID 37243914, 2023). "Intervention studies involving lipid-lowering treatments, such as statins, which is considered as the first-line treatment for lowering ApoB level, have not yielded sufficient evidence from clinical trials in favour of its therapeutic benefits in preventing cognitive decline or dementia." (PMID 36247924, 2022). "Our study provided further empirical evidence in line with these pathophysiological hypotheses for apolipoproteins, even in the absence of any, or very weak associations between circulating cholesterols and dementia, non-linear relationship between ApoB and dementia was observed." (PMID 36247924, 2022).
nonalcoholic fatty liver disease (15 papers, 2017 to 2025). "Many connections were immediately biologically plausible; for example, rs73001065 has been associated with a decreased risk for non-alcoholic fatty liver disease, which our data indicates may happen through reduced APOB levels." (PMID 39972214, 2025). "Further, in a more recent study, disruption of ApoB leads to high incidences of non-alcoholic fatty liver disease." (PMID 38419006, 2024). "Thus, we need to further investigate whether CPO-induced CD133 degradation affects EGR2 and apolipoprotein B expression levels, to overcome nonalcoholic fatty liver disease." (PMID 32397206, 2020). "Non-HDLc represents atherogenic lipoproteins such as LDLc, very low-density lipoproteins, and small dense LDL (apolipoprotein B), and the non-HDLc/HDLc ratio was detected to perform better than LDLc, HDLc or non-HDLc in estimating arterial stiffness and non-alcoholic fatty liver disease." (PMID 32660519, 2020). "In accordance with this hypothesis, it was already demonstrated that patients with nonalcoholic fatty liver disease (NAFLD) have increased serum concentration of TGs but not ApoB." (PMID 28871187, 2017).
Sepsis (15 papers, 2010 to 2025). Sepsis is defined as life-threatening organ dysfunction caused by a dysregulated host response to infection. "In the present study, the association between impaired apoB-depleted plasma’s anti-inflammatory capacity and the presence of sepsis depended on the HDL-C level." (PMID 38603717, 2024). "ApoB-depleted plasma’s anti-inflammatory capacity is reduced in sepsis patients and this association depends of HDL-C concentration." (PMID 38603717, 2024). "This study showed that apoB-depleted plasma’s anti-inflammatory capacity is significantly reduced in patients with sepsis, and that this association depends on the HDL-C concentration." (PMID 38603717, 2024). "Subgroup analysis was conducted to explore the association between sepsis severity and apoB-depleted plasma’s anti-inflammatory capacity." (PMID 38603717, 2024). "ApoB-depleted plasma’s anti-inflammatory capacity was associated significantly with the presence of sepsis in a univariable logistic regression analysis {odds ratio [95% confidence interval (CI)] = 2.60 [1.82–3.93]; p < 0.0001}." (PMID 38603717, 2024). "The aim of the study was to determine whether apoB-depleted plasma’s anti-inflammatory capacity is associated with the presence and/or severity of sepsis, and to explore its correlations with various laboratory and clinical parameters." (PMID 38603717, 2024). "Further studies are needed to compare the anti-inflammatory capacity of purely isolated HDL and apoB-depleted plasma in sepsis." (PMID 38603717, 2024). "In patients with sepsis, apoB-depleted plasma’s anti-inflammatory capacity correlates with disease severity and various inflammatory markers, such as the CRP level and WBC." (PMID 38603717, 2024). "In our study, the CRP level and WBC, generic inflammatory markers, correlated inversely with apoB-depleted plasma’s anti-inflammatory capacity in patients with sepsis, consistent with the concept of inflammation-induced HDL dysfunction." (PMID 38603717, 2024). "Univariable and multivariable logistic regression for the association between apoB-depleted plasma’s anti-inflammatory capacity (represented by VCAM-1 mRNA fold change value) and the presence of sepsis (n = 130)." (PMID 38603717, 2024). "Apo B levels was reported to be increased after Escherichia coli sepsis in an experimental model; in human sepsis, LPS-binding protein—that interacts with ApoB was found to be associated with LDL and VLDL particles." (PMID 31341447, 2019). "We find that, in response to severe sepsis and SIRS of other causes, the plasma levels of apoM demonstrate a decrease, which is more pronounced than those of apoAI and apoB." (PMID 22512779, 2012). "ApoB levels were less affected and was significantly lower than controls only in patients with severe sepsis and shock (P < 0.001)." (PMID 22512779, 2012). "Moreover, multivariable MR analysis showed that ApoA-I, ApoB, and LDL-C are causally associated with the risk of sepsis." (PMID 40934270, 2025). "In this cross-sectional study, we demonstrated that the anti-inflammatory capacity of apoB-depleted plasma was significantly reduced in patients with sepsis, and that this reduction was more pronounced in patients with than in those without septic shock and depended on the HDL-C concentration." (PMID 38603717, 2024). "LDL-C, TC, apoA-1, and apoB were significantly decreased in sepsis nonsurvivors and decreased apoA-1 predicted sepsis-related 30-day mortality." (PMID 34087197, 2021). "The aim was to determine the plasma concentrations of apoM during sepsis and systemic inflammatory response syndrome (SIRS) and correlate them to levels of apolipoprotein A-I (apoA1), apolipoprotein B (apoB), HDL-, and low-density lipoprotein (LDL)-cholesterol." (PMID 22512779, 2012).
Sepsis (continued). "Using lipid-laden THP1 cells and fibroblasts we were able to show that efflux capacity of HDL from both patients with severe sepsis or with Crohn's disease (active or in remission), either isolated using density gradient ultracentrifugation or using apoB precipitation, was not impaired." (PMID 22611487, 2012).
hyperuricemia (14 papers, 2014 to 2025). An abnormally high level of uric acid. "We have noticed the weakened association between ApoB and CKD in patients with hypertensive, hyperuricemia and hypohemia." (PMID 37124758, 2023). "Our study provided a hypothesis that ApoB may be an independent risk factor for CKD, especially in populations with hypertensive, hyperuricemia and hypohemia." (PMID 37124758, 2023). "In controls, associations with hypoalphalipoproteinemia, non-HDL-C, apolipoprotein B, hyperuricemia, TNF-α, IL-6, IL-15, valvular calcification, and subclinical hypothyroidism were observed." (PMID 33802675, 2021). "On the other hand, in controls, the polymorphisms were associated with hypoalphalipoproteinemia, non-HDL cholesterol, apolipoprotein B, hyperuricemia, TNF-α, IL-6, IL-15, valvular calcification, and subclinical hypothyroidism." (PMID 33802675, 2021). "The minor alleles of these polymorphisms were also associated with a low risk of IR (rs12617336 and rs17574) and HI (rs12617336), high risk of hyperuricemia (rs12617336), non-HDL-C > 160 mg/dL (rs17574), and apoB >110 mg/dL (rs17574)." (PMID 34178021, 2021).
unstable angina (14 papers, 2019 to 2025). "For instance, a case-control study examining patients with unstable angina diagnosed via electrocardiography found a significant association between elevated serum apoB and unstable angina, compared to controls (Al-Tu’ma, Mohammedad & Al-Sarraf, 2017)." (PMID 40852379, 2025). "The variables included in ourprediction model, including HbA1c, angina, ApoB, TBA, BNP, D-dimer, and Fg, arereadily available in clinical data and have been extensively studied for theiradverse effects on cardiovascular disease." (PMID 39867191, 2025). "Glycosylated hemoglobin (HbA1c), angina, apolipoprotein B (ApoB), total bile acid (TBA), B-type natriuretic peptide (BNP), D-dimer, and fibrinogen (Fg) were associated with the severity of lesions." (PMID 39867191, 2025). "Higher ratios of apolipoprotein B/apolipoprotein A-I were recorded in NSTE-ACS patients (versus stable angina patients)." (PMID 32449038, 2020). "Seven variables were screened using Lasso–logistic,including angina, HbA1c, TBA, ApoB, BNP, D-dimer, and Fg." (PMID 39867191, 2025).
aortic stenosis (13 papers, 2017 to 2026). Aortic valve stenosis is a aortic valve disease caused by the incomplete opening of the aortic valve. "They identified a significant association between a missense mutation in the APOB gene (rs1042031, E4181K) and aortic stenosis (p = 0.00001)." (PMID 39457433, 2024). "Lp(a) [lipoprotein (a)] is composed of apoB (apolipoprotein B) and apo(a) [apolipoprotein (a)] and is an independent risk factor for cardiovascular disease and aortic stenosis." (PMID 28729361, 2017). "Subjects who developed aortic stenosis during follow-up had a higher mean age at baseline (54.4 vs 44.6) and a higher proportion of males, as well as higher fasting glucose, lipid levels, apoB/apoA-1 ratio and CRP." (PMID 39915078, 2025). "PGS of ApoB and Lp(a) were significantly associated with aortic valve traits and aortic stenosis, while ApoA PGS was not." (PMID 41419685, 2026). "The risk of Lp(a) as an inde-pendent predictor of the progression of aortic stenosis could be explained by OxPL/apoB or OxPL/apo(a) lev-els." (PMID 27346583, 2018). "Additionally, they developed an ML-based model for predicting adverse outcomes in patients with symptomatic aortic stenosis and HFpEF after transcatheter aortic valve replacement using predictors, including age, NT-proBNP, fasting blood glucose, triglyceride or HDL ratio, and apolipoprotein B." (PMID 41397298, 2025).
Arthritis (13 papers, 2013 to 2025). Inflammation of a joint. "Mechanisms of arthritis self-limiting include coating MSU crystals with apolipoprotein B and E and clearing inflammatory cells by macrophages." (PMID 37069596, 2023). "ApoB was reported to aggravate arthritis by eliciting the production of TNF-α, IL-1β, and IL-6 through p38 mitogen-activated protein kinase and NF-κB pathways." (PMID 34996506, 2022). "ApoB/ApoA1 ratio was positively correlated with the concomitant of arthritis (p=.019), hCRP (p=.036), diastolic blood pressure (p=.014), and weight (p=.001)." (PMID 34996506, 2022). "Preclinical arthritis patients had a higher heart rate (p = 0.048) and lower TC (p = 0.006), HDL (p = 0.003) and ApoB levels (p = 0.011) compared to non-arthritis patients." (PMID 32745151, 2020). "ApoB may bind to enolase-1 expressed on the surface of immune cells to aggravate arthritis in RA patients." (PMID 34915859, 2021). "The subgroup analysis for the presence or absence of psoriatic arthritis showed that serum ApoA1 was significantly decreased in psoriasis both with and without arthritis, whereas serum ApoB was significantly increased in psoriasis with and without arthritis." (PMID 40137160, 2025). "Apolipoprotein B (ApoB), which is a low-density lipoprotein component, could bind to ENO1 to promote the secretion of inflammatory factors and aggravate arthritis." (PMID 36361568, 2022). "Preclinical arthritis patients (n = 188) had a higher heart rate (68 vs 63 bpm, p = 0.048) and lower cholesterol (5.2 mmol/l vs 5.5, p = 0.006), HDL (1.0 mmol/l vs 1.1, p0.003) and ApoB (0.85 g/l vs 0.91, p = 0.011) compared to non-arthritis patients (n = 367)." (PMID 32745151, 2020).
Cirrhosis (13 papers, 2014 to 2026). A chronic disorder of the liver in which liver tissue becomes scarred and is partially replaced by regenerative nodules and fibrotic tissue resulting in loss of liver function. "The variants affected cirrhosis risk similarly, but ApoB48/100 had a larger effect on HCC (P < 0.05).CONCLUSIONSRare APOB variants predispose individuals to advanced MASLD and HCC, with distinct contributions from disrupted VLDL and chylomicrons secretion." (PMID 41665936, 2026). "Loss-of-function or missense mutations within the APOB gene can result in a decrease in serum cholesterol and an increase in intrahepatic triglycerides that have been implicated in familial cases of steatohepatitis, cirrhosis, and hepatocellular carcinoma." (PMID 30355853, 2018). "Patients with HCC without cirrhosis had increased triglyceride, cholesterol, HDL-C, LDL-C, and ApoB levels compared to patients with cirrhosis." (PMID 30400953, 2018). "Overall, we observe the highest (5- to ninefold) increase in the normalized fucosylated intensity for the bi-antennary glycoform of the QVFPGLNYCTSGAYSNASSTDSASYYPLTGD glycopeptide of apolipoprotein B-100; the increase is significant in all the cirrhosis groups compared to the healthy control group." (PMID 34857845, 2021). "The germline genetic testing was limited to the 226 cancer-predisposition genes included in the CZECANCA panel, which was designed for the analysis of cancer predisposition but does not cover some of the known cirrhosis-predisposing genes (i.e., APOB, HFE, PNPLA3, SERPINA1)." (PMID 36612198, 2022). "We observed that NASH patients with cirrhosis have lower apoB ASR than noncirrhotic and healthy counterparts." (PMID 36737040, 2023).
gastric cancer (13 papers, 2016 to 2025). A primary or metastatic malignant neoplasm involving the stomach. "Clinical studies have shown that the level of ApoB/ApoA1 in gastric cancer patients is negatively correlated with the survival rate, while PDIA4 is positively correlated with the survival rate of gastric cancer patients." (PMID 34476221, 2021). "Previous literature has also reported that ApoB/ApoA-1 is an independent prognostic factor for gastric cancer." (PMID 32391278, 2020). "Additionally, risk of gastric cancer was significantly higher for individuals with lower levels of triglycerides (P < 0.0001), total cholesterol (P < 0.0001), HDL-cholesterol (P < 0.0001), LDL-cholesterol (P < 0.0001), apoA1 (P < 0.0001), and apoB (P < 0.0001)." (PMID 26817942, 2016).
gout (13 papers, 2010 to 2025). A condition characterized by painful swelling of the joints, which is caused by deposition of urate crystals. "High levels of VLDL triglyceride and its associated ApoB have been observed in gout." (PMID 28679452, 2017). "ApoB underscores the role of atherogenic lipoproteins in gout-CVD comorbidity, potentially exacerbated by urate crystal-induced endothelial injury." (PMID 41141353, 2025). "We found that the levels of TC, LDL-C, ApoB and LP(a) were higher in patients in the two gout groups than in the control patients (P < 0.05)." (PMID 24068523, 2014). "The apolipoprotein B (apo B), which is present on VLDL, regulates neutrophil response to MSU crystals and has been positively associated with gout." (PMID 25432151, 2014). "Besides that, ApoB and ApoE also exerts a key role in the resolution of acute gout through coating MSU crystal." (PMID 30863362, 2019). "Apolipoprotein B may have pleiotropic effects in determining HU and gout." (PMID 25432151, 2014). "The comparison of lipid and renal function indicators in the gout and control groups revealed that apolipoprotein B (APOB) and blood creatinine (CREA) levels were significantly higher in the gout group than in the control group." (PMID 38652726, 2024). "The therapeutic targets through which Simiao decoction alleviated gouty arthritis were p-STAT3, APOB, CASP8, c-FOS, PPARα, FN1, and LPL." (PMID 32670069, 2020).
lipid metabolism disorder (13 papers, 2014 to 2025). "Germline mutations in APOB also potentially cause diseases associated with lipid metabolic disorders, such as hypobetalipoproteinaemia and hypercholesterolaemia." (PMID 30206226, 2018). "If the gene encoding APOB has mutational changes, APOB structure and function would be affected and finally lead to lipid metabolism disorder, such as increase of plasma ApoB and LDL, decrease of HDL, etc." (PMID 26446158, 2015). "Previous studies suggested that Apolipoprotein AI (ApoAI) and apolipoprotein B (ApoB) gene polymorphisms may result in lipid metabolism disorders." (PMID 25248404, 2014). "The rs1042034, rs676210, and rs673548 in the ApoB gene were associated with a reduced risk of alcohol-induced ONFH, and confirmed the correlation between the ApoB/ApoA1 ratio and lipid metabolism disorders." (PMID 39058826, 2024). "Nowadays, due to the technological advancement of next-generation sequencing, the sequencing of the whole coding region and splice region of the APOB gene is available, therefore more FH and other lipid metabolism disorder-related alterations have been described." (PMID 35052492, 2022). "In this study, APOA4 and APOB were significantly downregulated in SBA, suggesting that lipid metabolism disorders may play an important role in the occurrence of SBA." (PMID 36171259, 2022). "In terms of lipid metabolic disorders, flavonoids have been found to produce therapeutic effects by reducing total cholesterol, triglycerides, low-density lipoprotein cholesterol (LDL-Cholesterol) and Apolipoprotein B (apoB) levels." (PMID 35391801, 2022).
cerebrovascular disease (12 papers, 2009 to 2025). "Although previous studies have shown the unfavorable roles of ApoB and the ApoB/A1 ratio in the cerebrovascular diseases and diabetes, scarce data assessed the associations of ApoB level and ApoB/A1 ratio with HbA1c." (PMID 35177752, 2022). "Therefore, simultaneous measurement of traditional lipid markers (including TG, TC, LDL-C, and HDL-C), ApoB, and ApoA-I is more conducive to risk assessment of cardiovascular and cerebrovascular diseases." (PMID 38274879, 2023). "Apolipoprotein B is the principal structural apolipoprotein in the LDL-C, and a high LDL-C level is a risk factor for aspirin resistance and cerebrovascular disease." (PMID 33746886, 2021). "With an increasing number of the three cardio-cerebrovascular disease manifestations, the ApoB/A1 ratio gradually showed an increasing trend." (PMID 31744496, 2019). "Future studies are needed to determine whether ApoB/ApoA-I can be used as a target for secondary prevention of cerebrovascular disease." (PMID 38274879, 2023).